PTPRO (protein tyrosine phosphatase receptor type O)
Diseases named in the same sentence as PTPRO in open-access papers (continued):
Sharing a sentence is not in itself a finding about the gene and the disease.
pancreatic cancers (1 paper, 2021). "Further GSEA analysis revealed several signaling pathways associate with PTPRO expression, which helps to understand the underlying carcinogenic functions of PTPRO in pancreatic cancer." (PMID 35003364, 2021). "Kaplan-Meier plotter database was employed to examine the link between PTPRO expression and clinical features, as well as immune cell enrichment levels of pancreatic cancer patients." (PMID 35003364, 2021). "Thereafter, in vitro tests proved that inhibition of PTPRO effected the growth of pancreatic cancer cells." (PMID 35003364, 2021). "Here, we further evaluated the effects of PTPRO inhibitor GP03 on cell apoptosis as well as cell cycle of pancreatic cancer cells." (PMID 35003364, 2021). "Based on the results, PTPRO expression showed an inverse relationship with tumor purity (r = -0.324, P = 1.45e-05) in pancreatic cancers." (PMID 35003364, 2021). "Bioinformatic analysis above suggested the potential oncogenic role of PTPRO in blood, breast, and pancreatic cancers." (PMID 35003364, 2021). "To confirm the oncogenic role of PTPRO, we knocked-down the expression of PTPRO in pancreatic cancer cells using lentiviral and measured the cell viability using Celigo and flow cytometry assays, which based on GFP-expressing cancer cells." (PMID 35003364, 2021). "Bioinformatic analysis revealed the potential oncogenic role of PTPRO in several cancer type, especially pancreatic cancer." (PMID 35003364, 2021). "In vitro tests indicated that inhibition of PTPRO impacts the cell growth, cell apoptosis as well as cell cycle in pancreatic cancer." (PMID 35003364, 2021). "To further elucidate the function of PTPRO in pancreatic cancer, Gene Set Enrichment Analyses (GSEA) we carried out using the TCGA dataset." (PMID 35003364, 2021). "Inspired by the results of analysis above, we speculated that PTPRO expression might be related to infiltration level of immune cells in pancreatic cancers." (PMID 35003364, 2021). "Taken together, our findings indicated that inhibition of PTPRO may serve as a new strategy for the treatment of pancreatic cancer." (PMID 35003364, 2021). "Moreover, small molecular PTPRO inhibitor GP03 not only induced cell apoptosis of pancreatic cancer cells, but also inhibited cell cycle progression in G2 and S phase." (PMID 35003364, 2021). "As expected, knock-down of the expression of PTPRO inhibited growth of pancreatic cancer cell." (PMID 35003364, 2021). "Our findings suggested PTPRO may serve as a potential drug target for pancreatic cancer." (PMID 35003364, 2021). "Our findings revealed that PTPRO might play a crucial role in the progression of pancreatic cancer." (PMID 35003364, 2021). "Moreover, small molecular PTPRO inhibitor could induce cell apoptosis and affect the cell cycle in pancreatic cancer." (PMID 35003364, 2021). "On the other hand, the expression of PTPRO indicated a weak correlation with CD4+ T cells (r = 0.031, P = 6.84e-01) and B cells (r = 0.025, P = 7.45e-01) in pancreatic cancers." (PMID 35003364, 2021). "In addition, PTPRO expression promoted the infiltration of CD8+ T, macrophages, dendritic cells, and neutrophils, in pancreatic cancers." (PMID 35003364, 2021). "Notably, PTPRO expression was positively related to the levels of CD8+ T cell infiltration (r = 0.668, P = 1.78e-23), neutrophils (r = 0.73, P = 1.00e-29), macrophages (r = 0.519, P = 3.45e-13) and dendritic cells (r = 0.817, P = 2.44e-42) in pancreatic cancers." (PMID 35003364, 2021).
prion disease (1 paper, 2026). A transmissible disease that is caused by a protein that is able to induce abnormal folding of normal cellular proteins, leading to characteristic spongiform brain changes, which are associated with neuronal loss without an inflammatory response. "RNA-seq analysis revealed that hypothalamic CYTB, ATP6, COX, ABLIM1, and ABI3 were significantly upregulated in IM group, whereas SHISA7 and PTPRO were significantly downregulated, with notable enrichment in prion disease, oxidative phosphorylation, and thermogenesis pathways." (PMID 41715947, 2026).
rectum cancer (1 paper, 2021). "However, PTPRO expression was linked to a better OS and RFS in rectum cancer." (PMID 35003364, 2021). "We further employed the Kaplan-Meier plotter database to evaluate the prognostic significance of PTPRO in pancreatic and rectum cancer samples, which are not included in the PrognoScan database." (PMID 35003364, 2021).
uterine carcinosarcoma (1 paper, 2021). A usually aggressive malignant neoplasm arising from the uterine corpus and less often the cervix. "However, PTPRO was downregulated in kidney chromophobe (KICH), kidney renal clear cell carcinoma (KIRC), uterine carcinosarcoma (UCS), uterine corpus endometrial carcinoma (UCEC), and kidney renal papillary cell carcinoma (KIRP), relative to the corresponding normal tissues." (PMID 35003364, 2021).
tumor (43 papers, 2007 to 2025). "CRISPR/Cas9-mediated STAT3 knockout was employed to evaluate the anti-tumor effects of PTPRO in STAT3-deficient cells." (PMID 38182570, 2024). "Further, the reduced expression level of PTPRO is associated with tumor size, poor histological differentiation, increased tumor depth, ERBB2, and Ki67 expression as well as shorter patient survival." (PMID 35431974, 2022). "PTPRO also plays a critical role in regulating cancer-associated inflammation and anti-tumor immunity." (PMID 34650968, 2021). "A number of studies have implicated that PTPRO participates in the regulation of macrophage-mediated inflammatory response, hepatic ischemia reperfusion injury, and tumor immunity." (PMID 34007244, 2021). "Adoptive cell transfer of c-MYC/miR-25–3 p–modified monocytes promoted tumor growth by downregulating PTPRO and causing a PD-L1–induced immunosuppression in an orthotopic tumor transplantation model." (PMID 32581055, 2020). "We found that the monocyte PTPRO was significantly associated with tumor size and tumor number, mainly due to its related increased PD-L1 expression, and potentially induced immunosuppression." (PMID 32581055, 2020). "As shown, tumor tissue PTPRO methylation was associated with significantly worse cancer-specific survival in the overall tumor group (log-rank test P = 0.0001)." (PMID 24919593, 2014). "Protein Tyrosine Phosphatase Receptor-type O (PTPRO) has recently been in the spotlight as a tumor suppressor, whose encoding gene is frequently methylated in cancers." (PMID 24090193, 2013). "Furthermore, the anti-tumor effect of PTPRO in LUAD was significant but compromised in STAT3-deficient cells." (PMID 38182570, 2024). "It remains to be investigated whether PTPRO levels in T‐Orgs are of equal diagnostic relevance as compared to the original tumour." (PMID 34841646, 2022). "Since PTPRO can suppress tumour progression and metastasis by targeting STAT3 and JAK217, we focused our research on the JAK2/YAP pathway." (PMID 40016288, 2025). "To better understand the mechanism of breast cancer lung metastasis, we first compared BC cell migration and invasion in mice with either wild-type or Ptpro-null tumours and identified the suppressive role of PTPRO in breast cancer lung metastasis." (PMID 40016288, 2025). "Bioinformatics analyses and assays of human cancer specimens and mouse tumour samples were performed to investigate PTPRO-regulated pathways and functions." (PMID 40016288, 2025). "Studies have shown that PTPRO in exosomes derived from tumor cells promoted the polarization of M1-like macrophages and modulated their associated functional phenotype." (PMID 38835784, 2024). "For example, PTPRO exhibits tumor-suppressive properties in chronic lymphocytic leukemia through negative regulating of B-cell receptor (BCR) signaling." (PMID 38182570, 2024). "As a result, PTPRO overexpression drastically suppressed tumor growth in nude mice, as evidenced by significantly lighter tumor weight and smaller tumor size in the PTPRO group compared with the vector group." (PMID 38182570, 2024). "In breast cancer, PTPRO in tumor-derived exosomes regulates tumor cell invasion and migration and is expected to become a therapeutic target." (PMID 39065585, 2024). "Pan-cancer analysis of The Cancer Genome Atlas (TCGA) cohort revealed distinguished expression of PTPRO in different tumor types." (PMID 38182570, 2024). "Increasing studies demonstrated the critical functions of PTPRO in tumor suppression of certain cancer types." (PMID 38182570, 2024). "Truncated PTPRO has been identified as a potent tumor suppressor that regulates immune cell growth, differentiation, activation, and immune responses, underscoring its potential role in tumor immunotherapy." (PMID 39065585, 2024). "The tumor suppressor PTPRO is highly enriched in the hippocampi of both humans and mouse, while reduced levels of PTPRO were found in the hippocampi of AD patients." (PMID 37485875, 2023).
tumor (continued). "In this study, we confirmed the relationship between PTPRO and the tumor immune microenvironment for the first time, which provided more theoretical support for guiding the immunotherapy of LUAD." (PMID 36816740, 2023). "Based on previous studies, PTPRO has been shown to act as a tumor suppressor in the development of various tumors." (PMID 36816740, 2023). "The receptor-type tyrosine-protein phosphatase O (PTPRO) is a member of the protein tyrosine phosphatases (PTPs) family that acts as a mediator of cell signaling pathways by inhibiting tumor proliferation and degeneration." (PMID 37508414, 2023). "Another study revealed that PTPRO suppress tumor cell proliferation and promotes apoptosis by dephosphorylating signal transducer and activator of transcription 3 (STAT3) in liver cancer." (PMID 36816740, 2023). "Tumor infiltration of CD8+ T cells was significantly higher in tumors with higher PTPRO expression than in tumors with low PTPRO expression (r = 0.914; P < 0.001)." (PMID 36003382, 2022). "At the same time, lapatinib treatment based on PTPRO level also reflects the significance of tumor precision treatment." (PMID 35431974, 2022). "The deletion of protein tyrosine phosphatase receptor type O (PTPRO) in mice (a tumor suppressor), resulted in severe autophagy impairment." (PMID 35887082, 2022). "Since PTPROt is involved in B cell development and activation via the BCR signaling pathway, it will be interesting to explore how PTPRO/PTPROt of TIBs to reshape tumor microenvironment and effect tumor immunotherapy." (PMID 34880876, 2021). "Taken together, these results demonstrated that tumor cell-derived exosomal PTPRO promoted macrophages to differentiate into M1-like phenotype likely by inactivating the STAT signaling with its dephosphorylate function." (PMID 34650968, 2021). "Nevertheless, little is known about the functional involvement of PTPRO expressed in tumor cells in regulating TME." (PMID 34650968, 2021). "We and others previously demonstrated that protein tyrosine phosphatase receptor type O (PTPRO) acts as a tumor suppressor in multiple cancer types." (PMID 34650968, 2021). "In contrast, we demonstrated that tumor-derived exosomal PTPRO promotes macrophages to differentiate into M1-like macrophages, resulting in inhibition of tumor cell invasion and migration." (PMID 34650968, 2021). "It has been reported that PTPRO can serve as a tumor suppressor and predictor for diagnosis and prognosis in various cancers." (PMID 34880876, 2021). "Protein tyrosine phosphatase receptor type O has been recognized as a tumor suppressor in multiple cancer types." (PMID 34650968, 2021). "PTPRO/PTPROt is also capable of positively enhancing anti-tumor immunity in both T cells and macrophages while brings about negative effects in several macrophage-related inflammatory diseases." (PMID 34880876, 2021). "Further, we confirmed that tumor-derived exosomal PTPRO induced macrophages to switch into a M1-like phenotype, leading to decreased migration and invasion abilities of tumor cells." (PMID 34650968, 2021). "Additionally, given the role of PTPRO in restricting tumor-promoting Jak/Stat signaling transduction that is associated with tumor immunity, recent studies have also begun to focus on the functional impact of PTPRO on immune cells residing in tumor microenvironment." (PMID 34880876, 2021). "Meanwhile, we revealed the underlying mechanism of macrophage polarization, which involved dephosphorylation of STATs in macrophages modulated by tumor cell-derived exosomal PTPRO." (PMID 34650968, 2021). "Further, we observed that tumor-derived exosomal PTPRO induced M1-like macrophage polarization, and regulated the corresponding functional phenotypes." (PMID 34650968, 2021). "Despite of the pro-inflammation effect of PTPRO, PTPRO in TAMs is found to positively regulate the immune response of T cells and thus suppress tumor progression." (PMID 34880876, 2021).
tumor (continued). "ERα was used as a transcription factor of PTPRO to up-regulate its expression and enhance its tumor suppressor effect." (PMID 35096574, 2021). "We found a significant decrease in PTPRO in HCC peripheral monocytes that was associated with increased PD-L1 expression in peripheral monocytes and tumor-associated macrophages (TAMs) in HCC." (PMID 32581055, 2020). "We have previously discovered a relationship between the low expression of protein tyrosine phosphatase, receptor type O (PTPRO) in tumor-infiltrating T cells and immunosuppression." (PMID 32581055, 2020). "We investigated TAM differentiation and the tumor growth–promoting effects of the c-MYC/miR-25–3 p/PTPRO axis using an orthotopic tumor transplantation model with adoptive cell transfer." (PMID 32581055, 2020). "Protein tyrosine phosphatase, receptor type O (PTPRO) has been identified as a tumor suppressor in several kinds of cancer, including CRC." (PMID 31827380, 2019). "The cell proliferation was inhibited and apoptosis was promoted in PTPRO overexpressing HCC cell lines, and tumor number and size were enhanced in PTPRO knockout mice." (PMID 29558404, 2018). "PTPRO was found to act as a tumor suppressor in human cancers such as chronic lymphocytic leukemia, lung, and breast cancer." (PMID 29558404, 2018). "Further, PTPROt, a truncated isoform of PTPRO, was shown to play an important role in anti-tumor immunity in HCC microenvironment in a mouse model." (PMID 29558404, 2018). "In HCC, PTPRO expression was significantly reduced in the tumor specimens compared with adjacent tissue, which is probably caused by hypermethylation on PTPRO promoter." (PMID 29558404, 2018). "In this study, we detected PTPRO methylation in the plasma of 34% (33/98) of patients; this value was significantly correlated with PTPRO methylation detected in tumor tissue." (PMID 24919593, 2014). "As an extension of our previously established conceptual framework, in which PTPRO downregulates tyrosine phosphorylation of multiple oncogenic pathways in breast carcinogenesis, we experimentally confirmed the functional association between PTPRO phosphatase activity and the JAK2–YAP axis." (PMID 40016288, 2025). "Besides, these results indicate the existence of other possible mechanisms contributing to PTPRO’s anti-tumor role." (PMID 38182570, 2024). "PC9 cells stably transfected with PTPRO or vector were injected into the tail vein of immunodeficient mice to determine whether PTPRO inhibited tumor metastasis in vivo." (PMID 38182570, 2024). "In this study, we evaluated the relationship between the expression level of PTPRO in LUAD and immune cell subsets in the tumor through multiple databases, and the results showed that the expression level of PTPRO significantly affected the infiltration of various immune cells." (PMID 36816740, 2023). "Our recent study indicated that tumor-derived exosomal PTPRO could ameliorate the immunosuppressive tumor microenvironment (ITM) and inhibit breast tumor cell metastasis by resetting tumor-associated macrophages (TAMs)." (PMID 36003382, 2022). "Additionally, given the regulatory functions of PTPRO in immune cells, we and other groups have begun to focus on the roles of PTPRO in tumor immunity." (PMID 36003382, 2022). "Therefore, it can be implied a novel role of PTPRO/PTPROt as a prohibitor of tumor immune escape, and PTPRO/PTPROt potentially serves as a promising candidate for future therapeutic interventions, shedding a new light on anti-tumor immunotherapy." (PMID 34880876, 2021). "PTPRO is a tumor suppressor and is abnormally expressed in various malignant tumors." (PMID 33462260, 2021). "Furthermore, we utilized TIMER 23, 24 (Immune Estimation Tumor Resource) to analyze the relationship between PTPRO and tumor-infiltrating immune cells in the various tumor microenvironments." (PMID 35003364, 2021).